DEPDC1B (DEP domain containing 1B)
Diseases named in the same sentence as DEPDC1B in open-access papers (continued):
Sharing a sentence is not in itself a finding about the gene and the disease.
breast carcinoma (continued). "DEP domain-containing protein 1B (DEPDC1B), which is located at chromosome 5 (5q12.1), was initially discovered by mRNA expression profiling in MDA-MB231 human breast cancer cells." (PMID 35095994, 2021). "Furthermore, we also revealed a novel mechanism in DEPDC1B-mediated USP5 deubiquitination of β-catenin, which led to the activation of the wnt/β-catenin signaling pathway and ultimately promoted breast cancer cell metastasis." (PMID 37642235, 2023). "In addition, we also proved that DEPDC1B, USP5, and β-catenin colocalize in breast cancer cells and that DEPDC1B promotes the deubiquitination of β-catenin by USP5." (PMID 37642235, 2023). "Here, we indicate that there is an interaction between DEPDC1B and β-catenin in breast cancer cells, but it is not clear whether DEPDC1B is also involved in the ubiquitin process." (PMID 37642235, 2023). "However, it is not clear whether DEPDC1B plays a role in breast cancer by affecting ubiquitin events." (PMID 37642235, 2023). "However, it is not known whether DEPDC1B plays a carcinogenic role in breast cancer by affecting invasion and migration." (PMID 37642235, 2023).
non-small cell lung carcinoma (5 papers, 2020 to 2023). A group of at least three distinct histological types of lung cancer, including non-small cell squamous cell carcinoma, adenocarcinoma, and large cell carcinoma. "In non-small cell lung cancer, DEPDC1B could enhance cell migration and invasion through the activation of Wnt/β-catenin signaling, and this biological effect could be inhibited by the depletion of LEF1 or TCF4." (PMID 35095994, 2021). "Notably, some studies demonstrated that the overexpression of DEPDC1B could be used as a prognostic biomarker to predict the outcomes of patients with prostate and non-small cell lung cancers." (PMID 35095994, 2021).
chordoma (4 papers, 2021 to 2024). Chordomas are rare malignant tumors arising from embryonic remnants of the notochord in axial skeleton. "Although DEP domain-containing protein 1B (DEPDC1B) is implicated in a variety of malignancies, its relationship with chordoma is unclear." (PMID 34330893, 2021). "The function of DEPDC1B in chordoma cells was clarified through loss-of-function assays in vitro and in vivo." (PMID 34330893, 2021). "Furthermore, the apoptosis percentage of shDEPDC1B group was significantly increased than that of shCtrl group (P < 0.001), indicating that the knockdown of DEPDC1B increased the apoptosis susceptibility of chordoma cells." (PMID 34330893, 2021). "Several recent studies (including our own) have revealed that EGFR-signaling dysbiosis modulated by CMTM3 and cMET exacerbated the chordoma process, and that DEPDC1B regulated ubiquitination of BIRC5 also promoted chordoma progression." (PMID 36248973, 2022). "As a consequence, BIRC5 was preliminarily identified as a downstream target of DEPDC1B in chordoma cells." (PMID 34330893, 2021). "Specifically, knockdown of DEPDC1B inhibits the malignant behavior of chordoma cells in vitro, such as reduction of proliferation, induction of apoptosis, and inhibition of migration." (PMID 34330893, 2021). "Meanwhile, BIRC5 overexpression reduced the inhibitory effects of DEPDC1B knockdown in chordoma cells." (PMID 34330893, 2021). "In this study, the unique role and potential molecular mechanism of DEPDC1B in chordoma were recognized." (PMID 34330893, 2021). "The malignant behaviors of DEPDC1B knockdown chordoma cells was significantly inhibited, which was characterized by reduced proliferation, enhanced apoptosis, and hindered migration." (PMID 34330893, 2021). "Because our research group is dedicated to the investigation of chordoma, we wondered the role of DEPDC1B in chordoma." (PMID 34330893, 2021). "On the other hand, upon the treatment of CHX (0.2 mg/mL, protein synthesis inhibitor), the protein stability of BIRC5 in shCtrl and shDEPDC1B chordoma cells was examined, indicating that DEPDC1B silencing induced a decrease of BIRC5 protein stability." (PMID 34330893, 2021). "As a consequence, the effects of alteration of DEPDC1B expression on chordoma cells was investigated in vitro." (PMID 34330893, 2021). "Moreover, BIRC5 overexpression reduced the inhibitory effects of DEPDC1B knockdown in chordoma cells." (PMID 34330893, 2021). "The effects of DEPDC1B on chordoma regulation was further elucidated by mouse xenograft model." (PMID 34330893, 2021). "As expected, downregulation of DEPDC1B suppressed growth of chordoma in vivo." (PMID 34330893, 2021). "Therefore, the biological function and potential molecular mechanism of DEPDC1B in chordoma were explored in this study." (PMID 34330893, 2021). "The molecular mechanism of chordoma regulated by DEPDC1B was preliminarily explored." (PMID 34330893, 2021). "Furthermore, molecular mechanism of DEPDC1B in chordoma cells was recognized by RNA sequencing and Co-Immunoprecipitation (Co-IP) assay." (PMID 34330893, 2021). "Therefore, overexpression of BIRC5 can reduce the inhibitory effect of DEPDC1B knockdown on the malignant behaviors of chordoma cells." (PMID 34330893, 2021). "Collectively, knockdown of DEPDC1B suppressed tumor growth of chordoma in vivo." (PMID 34330893, 2021). "In conclusion, DEPDC1B regulates the progression of human chordoma through UBE2T-mediated ubiquitination of BIRC5, suggesting that it may be a promising candidate target with potential therapeutic value." (PMID 34330893, 2021). "In this study, the biological role and molecular mechanism of DEPDC1B in chordoma were explored." (PMID 34330893, 2021). "Importantly, apoptosis repeat-containing 5 (BIRC5) was considered to be the downstream target of DEPDC1B involved in the progression of chordoma." (PMID 34330893, 2021).
chordoma (continued). "Moreover, overexpression of BIRC5 can reduce the inhibitory effect of DEPDC1B knockdown on the malignant behaviors of chordoma cells." (PMID 34330893, 2021). "Furthermore, simultaneous downregulation of BIRC5 and DEPDC1B may exacerbate the inhibitory effects of chordoma cells." (PMID 34330893, 2021). "Simultaneous downregulation of BIRC5 and DEPDC1B may exacerbate the inhibitory effects of chordoma." (PMID 34330893, 2021). "Therefore, the significant breakthrough that DEPDC1B regulates the progression of human chordoma through UBE2T-mediated ubiquitination of BIRC5 may provide a valuable target for molecular therapy of chordoma patients." (PMID 34330893, 2021). "Not surprisingly, the molecular mechanism of chordoma cell apoptosis induced by DEPDC1B knockdown is complex, which required the participation of a series of apoptosis-related factors." (PMID 34330893, 2021). "In particular, the knockdown of DEPDC1B resulted in not only a significant upregulation of Caspase3, sTNF-R1, but also downregulation of Bcl-2, CD40, HSP27, IGF-1sR, XIAP, Livin, Survivin in chordoma cells." (PMID 34330893, 2021). "DEPDC1B regulates the progression of human chordoma through UBE2T-mediated ubiquitination of BIRC5, which may be a promising candidate target in molecular therapy of chordoma patients." (PMID 34330893, 2021).
liver cancer (4 papers, 2021 to 2025). An epithelial or non-epithelial malignant neoplasm that arises from the liver. "For example, several intronic variants within the DEP domain containing 1B (DEPDC1B), such as rs10939856 and rs1379116, displayed P-values around 0.03 in the non-integrated conditional logistic regression analyses with the liver cancer dataset." (PMID 41180965, 2025). "Among these characteristic genes, DEPDC1, DEPDC1B, PRR11, and TRIP13 were risk factors for liver cancer patients." (PMID 36785674, 2023). "The DEPDC1B protein was strongly expressed in liver cancer, compared with that in other cancers using HPA072558 antibody (Atlas Antibodies Sigma-Aldrich)." (PMID 35095994, 2021). "In liver cancer, the genes DEPDC1, DEPDC1B, PRR11, and TRIP13 have been explored in previous studies." (PMID 36785674, 2023). "Meanwhile, DEPDC1, DEPDC1B, CALCRL, PRR11, and TRIP13 were significantly upregulated in liver cancer tissue, yet NGFR was downregulated." (PMID 36785674, 2023).
neuroblastoma (3 papers, 2019 to 2022). Neuroblastoma (NB) is the most common solid, extracranial childhood tumor. "Taken together, the data suggest that lncNB1, its binding partner RPL35 and their targets E2F1 and DEPDC1B are required for neuroblastoma cell proliferation and survival." (PMID 31690716, 2019). "Alamar blue assays and flow cytometry analyses of Annexin V positively stained cells showed that knocking down lncNB1 or DEPDC1B expression for 48 h was too early to have an effect on neuroblastoma cell proliferation or survival." (PMID 31690716, 2019). "Thus, our data demonstrate that lncNB1, its binding protein RPL35 and their target protein E2F1 and target gene DEPDC1B induce neuroblastoma cell proliferation and survival." (PMID 31690716, 2019). "The GTPase-activating protein DEPDC1B then induces ERK protein phosphorylation and the stabilization of the N-Myc protein in neuroblastoma cells." (PMID 35095994, 2021). "Taken together, the data suggest that lncNB1, RPL35, and E2F1 regulate DEPDC1B expression in human neuroblastoma tissues, and that high levels of lncNB1, DEPDC1B, RPL35, and E2F1 expression in tumor tissues predict poor prognosis in neuroblastoma patients." (PMID 31690716, 2019). "We next investigated if lncNB1, DEPDC1B, RPL35, or E2F1 is required for neuroblastoma cell proliferation and/or survival." (PMID 31690716, 2019). "In addition, in human neuroblastoma tissues, lncNB1, E2F1, or RPL35 RNA expression positively correlates with DEPDC1B RNA expression, and high levels of lncNB1, E2F1, RPL35, or DEPDC1B expression predict poorer patient outcome." (PMID 31690716, 2019). "As high levels of lncNB1, RPL35, E2F1, and DEPDC1B expression in tumor tissues correlate with poor prognosis in neuroblastoma patients, our findings identify lncNB1, RPL35, and DEPDC1B as important co-factors for N-Myc-driven oncogenesis and provide therapeutic targets for neuroblastoma." (PMID 31690716, 2019).
colorectal cancer (2 papers, 2021 to 2024). A primary or metastatic malignant neoplasm that affects the colon or rectum. "While a recent study on colorectal cancer revealed that DEPDC1B promotes the proliferation and migration of colorectal cancer cells while inhibiting apoptosis, the role of DEPDC1B in the tumor immune microenvironment of COAD has yet to be investigated." (PMID 39087856, 2024).
lung adenocarcinoma (2 papers, 2021 to 2023). A carcinoma that arises from the lung and is characterized by the presence of malignant glandular epithelial cells. "The relationship between the expression of DEPDC1B and tumor characteristics in patients with lung adenocarcinoma under TCGA." (PMID 34032605, 2021). "The results of TCGA about lung adenocarcinoma showed that the expression level of DEPDC1B was significantly correlated with the pathologic T, pathologic N, tumor stage, and gender." (PMID 34032605, 2021).
breast ductal carcinoma (1 paper, 2021). "In the Richardson dataset, the CCDC167 gene and its co-expressed genes, such as SAC3D1, SPC24, CENPM and DEPDC1B, were substantially upregulated in breast ductal carcinoma compared to the normal group." (PMID 33461170, 2021).
colon adenocarcinoma (1 paper, 2024). "We analyzed the differential expression and prognostic significance of DEPDC1B in colon adenocarcinoma (COAD) using the R package “limma” and the Gene Expression Profiling Interactive Analysis (GEPIA) website." (PMID 39087856, 2024).
cutaneous melanoma (1 paper, 2022). A primary melanoma arising from atypical melanocytes in the skin. "Here, we found that increased expression of DEPDC1B in cutaneous melanoma was significantly associated with a poor prognosis." (PMID 35088579, 2022). "Here, it is found that high transcript levels of DEP domain containing 1B (DEPDC1B) in cutaneous melanomas are significantly associated with a poor prognosis." (PMID 35088579, 2022). "Our TCGA analysis revealed that DEPDC1B mRNA level was elevated in cutaneous melanoma and was correlated with poor survival." (PMID 35088579, 2022).
lymph node metastasis (1 paper, 2023). "The results showed that DEPDC1B was correlated with age, lymph node metastasis, and clinical stage." (PMID 37642235, 2023). "However, our tissue chip analysis showed that DEPDC1B expression was only correlated with lymph node metastasis (χ2 = 9.098, P = 0.028) and positively correlated with poor prognosis (χ2 = 5.487, P = 0.019) and resulted in poor OS." (PMID 37642235, 2023).
metastatic melanoma (1 paper, 2022). A melanoma that has spread from its primary site to another anatomic site. "The SOX10‐regulated DEPDC1B expression to stabilize SCUBE3 for promoting angiogenesis and metastasis was further supported by their high correlation of expression with microvessel density in metastatic melanoma specimens." (PMID 35088579, 2022). "We detected overlapping expressions of cytoplasmic DEPDC1B and SOX10 transcription factor in a large percentage of nevus, primary, and metastatic melanomas (86/98; 87.8%) compared with specimens expressing DEPDC1B alone (11/98; 11.2%) or expressing neither protein (1/98; 1%)." (PMID 35088579, 2022).
psoriasis (1 paper, 2024). An autoimmune condition characterized by red, well-delineated plaques with silvery scales that are usually on the extensor surfaces and scalp. "We found that core genes (TOP2A, MELK) were highly expressed in psoriasis samples and lowly expressed in normal tissue samples, while DEPDC1B, CCNA2, DLGAP5, NUF2, ASPM were lowly expressed in psoriasis samples." (PMID 38382096, 2024). "The gene expression heatmap showed high expression of core genes (TOP2A, MELK) in psoriasis samples, while DEPDC1B, CCNA2, DLGAP5, NUF2, ASPM were lowly expressed in psoriasis samples." (PMID 38382096, 2024).
rhabdomyosarcoma (1 paper, 2020). A rare aggressive malignant mesenchymal neoplasm arising from skeletal muscle. "DEPDC1B was expressed in human Rh30 rhabdomyosarcoma cells, where DEPDC1B or RHOA knockdown promoted myogenic differentiation, but without influencing proliferation." (PMID 31825138, 2020). "This analysis revealed that DEPDC1B was expressed at a higher level in rhabdomyosarcoma tumours compared to the skeletal muscle biopsies." (PMID 31825138, 2020). "DEPDC1B was expressed in human Rh30 rhabdomyosarcoma cells at a higher level than in myoblasts, and while DEPDC1B down‐regulation did not affect proliferation, it did promote myogenic differentiation." (PMID 31825138, 2020). "Expression dynamics of DEPDC1B were examined in murine and human myoblasts and rhabdomyosarcoma cells in vitro by RT‐qPCR and/or immunolabelling." (PMID 31825138, 2020). "DEPDC1B is overexpressed in many cancers, and we found higher expression of DEPDC1B in human rhabdomyosarcoma compared to skeletal muscle, and in Rh30 (ARMS) cells compared to human C25Cl48 myoblasts." (PMID 31825138, 2020). "DEPDC1B overexpression also increases phosphorylation of ERK,3, 5 and the MEK/ERK pathway controls myoblast proliferation, while MEK inhibition in RAS‐mutated rhabdomyosarcoma can induce myogenic differentiation." (PMID 31825138, 2020).
serous ovarian cancer (1 paper, 2023). "Immunohistochemical staining of 60 high-grade serous ovarian cancer (HGSOC) showed that DEPDC1B expression was associated with response to first line chemotherapy, and DEPDC1B expression was higher in platinum-resistant patients than in platinum-sensitive patients." (PMID 37056386, 2023).
tumor (24 papers, 2014 to 2025). "DEPDC1B expression in COAD is associated with tumor‐infiltrating immune cells, immune checkpoints, TMB, and MSI‐H in the tumor immune microenvironment." (PMID 39087856, 2024). "Correlations between DEPDC1B expression and tumor‐infiltrating immune cells, immune checkpoints, tumor mutational burden (TMB), and microsatellite instability (MSI) status were examined using Spearman correlation analysis and CIBERSORT." (PMID 39087856, 2024). "Aberrant expression of DEPDC1B is implicated in the development of various tumor types, as highlighted in multiple studies." (PMID 39087856, 2024). "In the univariate Cox analysis, tumor stage, T classification, and DEPDC1B expression were all independent risk factors for OS (p = 1.12e-06, 5.82e-07, and 0.01, respectively)." (PMID 35095994, 2021). "In a word, the expression of DEPDC1B increased with the progression of tumor malignancy, which was also positively associated with high risk of tumor recurrence through the Kaplan–Meier survival analysis." (PMID 32684847, 2020). "According to above in vitro loss-of-function experiments, we speculated that DEPDC1B played essential roles in ESCC tumor growth in vivo." (PMID 35706026, 2022). "Analysis using the CIBERSORT database and Spearman correlation revealed that DEPDC1B correlated with four types of tumor‐infiltrating immune cells." (PMID 39087856, 2024). "Further investigation into the correlation between DEPDC1B expression and tumor‐infiltrating immune cells using Spearman correlation analysis revealed significant associations with various immune cell types." (PMID 39087856, 2024). "We found that DEPDC1B interference significantly inhibited tumor invasion and migration in vitro and tumor metastasis in vivo." (PMID 37642235, 2023). "Kaplan-Meier analysis further confirmed that patients with high tumor DEPDC1B expression had worse OS (P = 0.0054) and PFS (P = 0.0152)." (PMID 37056386, 2023). "As expected, the signal intensity of DEPDC1B in tumor tissue is stronger than that in normal tissue." (PMID 35706026, 2022). "In this study, it was found that DEPDC1B expression was higher in CCA tissues than in normal tissues, or in CCA tissues with a more advanced tumor grade, showing the potential participation of DEPDC1B in CCA development." (PMID 36568241, 2022). "Clinical tissue-related detection showed that the expression level of DEPDC1B in tumor tissues was significantly higher than that in normal tissues and was positively correlated with tumor grade." (PMID 36568241, 2022). "The simulation of in vivo CCA growth in the xenograft animal models further demonstrate the DEPDC1B knockdown-induced suppression of tumor growth." (PMID 36568241, 2022). "The results indicated that DEPDC1B expression was positively correlated with tumor infiltrate, lymphatic metastasis and stage in patients with ESCC (p < 0.001)." (PMID 35706026, 2022). "Meanwhile, the prognostic analysis was performed based on the clinical information of TCGA-ESCA samples, suggested that the expression of DEPDC1B was significantly correlated with tumor stage (p < 0.05)." (PMID 35706026, 2022). "Firstly, expression of DEPDC1B was performed based on the 161 tumor and 11 normal samples in the Cancer Genome Atlas (TCGA) database." (PMID 35706026, 2022). "Accordingly, subcutaneous and tail vein injection of DEPDC1B OE cells in immunodeficient mice resulted in enhanced tumor growth and lung colonization." (PMID 35088579, 2022). "The exploration of downstream mechanisms further recognized the involvement of CDK1, which is a critical regulatory factor in cell cycle and a well-known tumor promotor, in DEPDC1B-induced promotion of CCA." (PMID 36568241, 2022). "Subsequently, the expression level of DEPDC1B in ESCC was verified based on the tissue microarrays (tumor, n = 266; normal, n = 39) from clinical ESCC patients using immunohistochemical experiments." (PMID 35706026, 2022).